OTOG (otogelin)
Description:
Glycoprotein specific to acellular membranes of the inner ear. May be required for the anchoring of the otoconial membranes and cupulae to the underlying neuroepithelia in the vestibule. May be involved in the organization and/or stabilization of the fibrillar network that compose the tectorial membrane in the cochlea. May play a role in mechanotransduction processes (By similarity).
Synonyms: OTGN; mlemp; FLJ46346; DFNB18B
Tractability: Antibody: UniProt places it where antibodies can reach, with medium confidence; UniProt predicts a signal peptide or a membrane-spanning region; its Gene Ontology location is reachable by antibodies, with medium confidence.
Gene: Protein-coding gene on chromosome 11 (17,547,259 to 17,647,150, forward strand). Ensembl gene ENSG00000188162.
Subcellular location: Apical cell membrane; Secreted, extracellular space
Pathways (Reactome):
Sensory Perception: Sensory processing of sound by outer hair cells of the cochlea
Gene Ontology:
Molecular function: extracellular matrix structural constituent; alpha-L-arabinofuranosidase activity
Biological process: L-arabinose metabolic process; nervous system development
Cellular component: apical plasma membrane; extracellular matrix; extracellular region
Genetic constraint (gnomAD): Loss-of-function variants: 286 observed, 289.02 expected, observed/expected ratio (o/e) 0.99, 90% interval 0.9 to 1.09. The upper end of that interval is the gene's LOEUF score, 1.09, which puts it in group 4 of 6, group 1 being the genes least tolerant of losing a copy. Missense variants: 3,836 observed, 3,681.7 expected, observed/expected ratio (o/e) 1.04, 90% interval 1.01 to 1.07. Synonymous variants: 1,489 observed, 1,483 expected, observed/expected ratio (o/e) 1, 90% interval 0.96 to 1.05.
Gene-disease validity (ClinGen):
ClinGen rates the evidence that OTOG causes each of these diseases.
nonsyndromic genetic hearing loss (autosomal recessive): Definitive.
Homologues: Orthologues: chimpanzee OTOG (98% identical), macaque OTOG (95% identical), dog OTOG (84% identical), pig OTOG (84% identical), rabbit OTOG (84% identical), mouse Otog (82% identical), rat Otog (81% identical), guinea pig OTOG (80% identical), tropical clawed frog OTOG (45% identical), zebrafish otog (42% identical). Paralogues in human: OTOGL (32% identical), VWF (24% identical), MUC5AC (22% identical), MUC5B (20% identical), FCGBP (16% identical), MUC19 (15% identical), MUC6 (15% identical), MUC2 (13% identical), ZAN (13% identical), TECTA (12% identical), KCP (11% identical), CRIM1 (7% identical), and 7 more.
Diseases named in the same sentence as OTOG in open-access papers:
OTOG is named in the same sentence as 24 diseases in open-access papers, as found by Europe PMC text mining. Sharing a sentence is not in itself a finding about the gene and the disease. The quoted sentences say what the papers report.
deafness (17 papers, 2015 to 2025). An inherited or acquired condition characterized by the complete loss of the ability to hear from one or both ears. "Otogelin is a TM protein related to secreted epithelial mucins and defects in otogelin cause a rare genetic form of deafness characterized by congenital mild-to-moderate SNHL22." (PMID 37284494, 2023). "Although human OTOG mutations have been linked to deafness, the biological function of OTOGL in male germ cell development remains enigmatic." (PMID 34174893, 2021). "The gene disrupted in eis is otogelin (otog); mutations in the human OTOG gene have recently been identified as causative for deafness and vestibular dysfunction (DFNB18B)." (PMID 25758224, 2015). "In addition, proband 42 was endowed with a homozygous missense variant, c.7454del p.(Arg2485Hisfs*77) in OTOG, which causes autosomal recessive deafness (DFNB18B; OMIM 614945) and may aggravate the HI phenotype." (PMID 34148116, 2022). "It was suspected that variants in few genes like STRC, GJB2, SLC26A4, OTOG or TECTA may explain the hearing loss for the majority of individuals in our cohort as is the case in many other world populations for the individuals with moderate to severe deafness." (PMID 32681043, 2020). "Genes from the CAPZA family were involved with the regulation of the growth of actin filament and associated deafness (e.g., PLS1, LHFL5, OTOG, ESPN, and ESPNL)." (PMID 41465109, 2025). "It has been shown that mutations in Otogelin and α-Tectorin impair otolith seeding, and mutations in their human orthologs OTOG and TECTA cause deafness." (PMID 33326993, 2021). "There is evidence that strong coupling of kinocilium to the overlying accessory structures requires the proteins otogelin (OTOG gene) and α-Tectorin (TECTA gene), mutations of which can cause deafness and vestibular dysfunction." (PMID 30565972, 2019). "The analysis of NGS data led to the identification of five novel variants in the known deafness genes MYO15A, LOXHD1, TBC1D24, and OTOG, all of which were associated with pathogenicity, and categorized according to the ACMG guidelines." (PMID 30139988, 2018). "In this study, we used NGS technology, which led to the identification of novel alleles in SLC26A4, MYO15A, OTOG, LOXHD1, and TBC1D24 that are associated with deafness." (PMID 30139988, 2018). "In humans, mutations in OTOG and TECTA cause deafness and, in some cases, vestibular dysfunction, making the einstein and rolling stones zebrafish mutants new models of these disorders." (PMID 25758224, 2015). "Notably, mutations in both OTOG and MYO7A have been associated with deafness in humans and in mice, but only MYO7A mutations have been associated with hydrocephalus." (PMID 38100419, 2023). "In the present study, we have also identified the missense/non-sense heterozygous variants in the OTOG p.(Val1813Gly), SLC26A4 p.(Tyr556∗) CDH23 p.(Ala1631Val), GJB2 p.(Arg165Trp), and MYO15A p.(Arg1965His) genes which are predominant to cause deafness among Indian populations." (PMID 34113375, 2021).
hearing loss (10 papers, 2015 to 2025). "Mutation of the gene encoding otogelin causes autosomal-recessive, non-syndromic, moderate hearing loss associated with severe imbalance, delayed motor development, and dizziness." (PMID 34589045, 2021). "NGS identified a homozygous variant in exon 4 of the OTOG gene, c.330C>G, p.Tyr110*, in seven patients with moderate sensorineural hearing loss." (PMID 31645975, 2019). "In conclusion, we identified the variant c.330C>G, p.Tyr110* in OTOG in seven patients of four families with moderate hearing loss in the Japanese population." (PMID 31645975, 2019). "In this present study, we have identified and characterised a new recessive ENU-induced mutation in the otogelin gene, named Otogvbd/vbd, inducing a moderate hearing impairment." (PMID 26636018, 2015). "To date, 44 causative OTOG variants have been reported to cause non-syndromic hearing loss." (PMID 39858607, 2025). "Mutations in the OTOG gene encoding Otogelin in humans result in moderate hearing impairment." (PMID 35958995, 2022). "However, only eight families, including our four families, with hearing loss caused by OTOG variants have been reported to date, and this is the first report of hearing loss caused by this variant in the Japanese population." (PMID 31645975, 2019). "However, the genotype–phenotype correlation is not clear, as only eight families, including our four families, with hearing loss caused by OTOG variants have been reported to date." (PMID 31645975, 2019). "Based on the allele frequency in the 1000 Genomes Project and in this study, hearing loss caused by the OTOG gene might be more common than reported previously." (PMID 31645975, 2019). "In addition, mutations in the OTOG gene encoding Otogelin cause moderate hearing impairment, which may be associated with vestibular dysfunction in humans." (PMID 35958995, 2022). "Testing for this gene, OTOG, which encodes a protein expressed in sensory cells of the inner ear, could thus be an important complement to newborn hearing screening for individuals with a family history of hearing loss who may benefit from early medical intervention." (PMID 31645975, 2019). "However, several OTOG gene variants are associated with AR-NSHL, presenting as mild-to-moderate sensorineural hearing loss." (PMID 39858607, 2025). "Otogelin and Otogelin-like are TM proteins associated with secreted epithelial mucins, and defects in either result in DFNB18B and DFNB84B hereditary deafness, both of which are respectively characterized by congenital mild to moderate hearing impairment." (PMID 35958995, 2022). "Mutations of the genes encoding OTOG (otogelin, DFNB18B), OTOGL (otogelin-like, DFNB84B), and TECTA (α-tectorin, DFNA8/12, DFNB21) have been associated with hearing loss in humans, with occasional reports of vestibular hyporeflexia or vertigo in patients with OTOG or TECTA defects." (PMID 35444606, 2022). "Although rare variants in TECTA, OTOG, and OTOGL have been associated with hearing loss, none of the variants identified in the current meta-analysis associate with hearing loss, identified by ICD-10 codes H90 and H91, nor any rare variants in the six GWAS candidate genes." (PMID 34620984, 2021). "However, it has not been clarified whether OTOG-associated hearing loss in humans is congenital or progresses early after birth." (PMID 31645975, 2019).
Meniere disease (6 papers, 2022 to 2025). A disease of the inner ear (labyrinth) that is characterized by fluctuating sensorineural hearing loss; tinnitus; episodic vertigo; and aural fullness. "Studies have linked OTOG mutations to noise-induced hearing loss and familial Meniere’s disease, while OTOG and OTOGL variants have been associated with vertigo risk." (PMID 40901670, 2025). "Recently, it was revealed that familial Meniere’s disease affects both cochlear and vestibular organs through the enriched genetic burden of rare variants in OTOG and GJD3." (PMID 38610765, 2024). "New studies report that the hearing loss profile does not only affect the low frequency in the early stages; however, a flat sensorineural hearing loss was observed in patients with familial Meniere’s disease and mutations in OTOG and MYO7A." (PMID 35683514, 2022). "Moreover, multiple rare missense variants in the OTOG gene are related to 33% familial Meniere disease." (PMID 36313500, 2022).
Vertigo (3 papers, 2021 to 2025). An abnormal sensation of spinning while the body is actually stationary. "Here, we report an association between vertigo in humans and a missense mutation in OTOG (Thr375Ser, rs7130190-T, EAF = 16.2%, P = 9.0 × 10−14, OR = 1.08) and OTOGL (Gln1102His, rs10862089-T, EAF = 7.50%, P = 1.2 × 10−13, OR = 1.11)." (PMID 34620984, 2021).
neurosensorial deafness (2 papers, 2020 to 2025). "Background/Objectives: The OTOG gene is responsible for autosomal recessive non-syndromic sensorineural hearing loss and is assigned as DFNB18B." (PMID 39858607, 2025).
age (1 paper, 2015). A temporal measurement of the time period elapsed since an identifiable point in the life cycle of an organism. "Genes that encode components of the otoconial membrane, such as OTOG or TECTA, might be good candidates for genetic predisposition to this disorder or for understanding age-related vestibular dysfunction." (PMID 25758224, 2015).
cone-rod dystrophy (1 paper, 2022). Inherited retinal dystrophies that belong to the group of pigmentary retinopathies. "In three of the USH cases, additional variants in genes for non-syndromic HI (OTOG, TECTA) or ABCA4-related VI (Stargardt disease, cone-rod dystrophy, and RP) may modify/aggravate the phenotype (left)." (PMID 34148116, 2022).
Hyperhidrosis (1 paper, 2020). Abnormal excessive perspiration (sweating) despite the lack of appropriate stimuli like hot and humid weather. "Nevertheless, at the moment, we cannot exclude that acrocyanosis and palmoplantar hyperhidrosis might represent unusual phenotypic manifestations of LARP7, OTOG, or a combination of both." (PMID 32244554, 2020). "This patient also presented acrocyanosis and palmoplantar hyperhidrosis, which might represent unusual phenotypic manifestations of LARP7, OTOG, or a combination of both." (PMID 32244554, 2020).
OTOG also shares sentences with these, for which no sentence is quoted: autosomal recessive deafness (3 papers); Hearing impairment (3); cancer (2); Alazami syndrome (1); auditory neuropathy (1); colorectal cancer (1); cranioectodermal dysplasia (1); developmental delay (1); gastric cancer (1); hematological cancers (1); Hip dysplasia (1); Hydrocephalus (1); infection (1); multiple epiphyseal dysplasia (1); oral squamous cell carcinoma (1); Stargardt disease (1).